RN7SL800P (RNA, 7SL, cytoplasmic 800, pseudogene)
Gene: Miscellaneous RNA gene on chromosome 17 (62,005,737 to 62,006,016, reverse strand). Ensembl gene ENSG00000242398.
Homologues: Orthologues: chimpanzee Metazoa_SRP (99% identical), macaque Metazoa_SRP (93% identical). Paralogues in human: RN7SL1 (74% identical), RN7SL2 (74% identical), RN7SL3 (74% identical), RN7SL664P (74% identical), RN7SL597P (73% identical), RN7SL448P (73% identical), RN7SL122P (72% identical), RN7SL126P (72% identical), RN7SL709P (72% identical), RN7SL567P (72% identical), RN7SL186P (72% identical), RN7SL220P (72% identical), and 702 more.